MGMT (O-6-methylguanine-DNA methyltransferase)
Diseases named in the same sentence as MGMT in open-access papers (continued):
Sharing a sentence is not in itself a finding about the gene and the disease.
glioblastoma (continued). "Arrays can also report promoter methylation at clinically relevant loci, most notably MGMT in glioblastoma, which informs temozolomide responsiveness; although often performed by separate assays, MGMT status can be extracted from array data." (PMID 41487568, 2025). "The GLASS consortium showed that shifts in MGMT methylation and expression directly tie into drug resistance and tumor evolution in glioblastoma, revealing layers of complexity that routine biopsies miss." (PMID 40895460, 2025). "In fact, the only biomarker predicting response to a treatment which has some success in treating glioblastoma is methylation of the MGMT promoter predicting response to TMZ." (PMID 39915814, 2025). "Crucially, MGMT promoter methylation is one of the most accurate predictive indicators in the treatment of glioblastoma, as supported by systematic reviews and meta-analyses." (PMID 41311621, 2025). "Pseudoprogression after radiotherapy or chemoradiotherapy is reported at higher rates in humans with MGMT promoter methylation in glioblastoma multiforme." (PMID 40417366, 2025). "Examples include the breast cancer gene 1 (BRCA1) in ovarian and breast cancer, the Von Hippel–Lindau tumor suppressor (VHL) in clear renal cell carcinoma and the O-6-methylguanine-DNA methyltransferase (MGMT) repair gene in glioblastoma (GB)." (PMID 38473745, 2024). "In glioblastoma, the analysis of MGMT methylation patterns significantly impacts prognosis and treatment response." (PMID 38674436, 2024). "An increasing body of research has concentrated on enhancing the sensitivity of tumors, particularly glioblastoma, to temozolomide treatment by targeting MGMT through various approaches." (PMID 38255825, 2024). "For instance, in glioblastoma and sporadic colorectal cancer, MGMT and MLH1 promoter methylation analyses through methylation‐sensitive pyrosequencing are employed for diagnostic and prognostic purposes." (PMID 38374872, 2024). "A methylated MGMT promoter showed a survival benefit in both neural subgroups, but a striking difference in low-neural glioblastoma with a median overall survival difference of 12.0 months depending on the MGMT promoter methylation status (P < 0.0001)." (PMID 38760585, 2024). "In the specific context of recurrent glioblastoma multiforme, a notable correlation has been observed between the hypermethylation status of the MGMT gene and a more favorable clinical outcome." (PMID 39055560, 2024). "In a study conducted by Yang and colleagues in 2022, the detection of methylation levels in the O6-methylguanine-DNA methyltransferase (MGMT) gene emerged as a critical endeavor for the diagnosis, prognosis, and treatment of glioblastoma." (PMID 38732975, 2024). "There remains a dearth of studies on impact of MGMT methylation of unresectable IDH- wildtype glioblastoma patients after WHO 2021 updated classification." (PMID 39367282, 2024). "Another similarity to glioblastoma is the prognostic value of the MGMT promoter status for survival." (PMID 39545524, 2024). "In conclusion, the rate of treatment-associated changes in the CENTRIC database was low compared to previous studies in newly diagnosed MGMT promoter-methylated glioblastoma." (PMID 38219019, 2024). "It is also noteworthy that none of our recruited patients with O6-methylguanine-DNA methyltransferase (MGMT)-positive glioblastomas were treated with tumor-treating fields, while this treatment method should additionally be offered to each eligible patient." (PMID 38707095, 2024).
glioblastoma (continued). "One study reported lower LINE-1 methylation levels in glioblastomas compared to low-grade gliomas, and higher LINE-1 methylation levels were associated with MGMT promoter methylation and longer survival of glioblastoma patients." (PMID 38183430, 2024). "High levels of ZEB1 downregulated tumor suppressor miR-200c, and low miR-200c induced MYB expression in primary glioblastoma cells, followed by increased O-6-methylguanine DNA methyltransferase (MGMT) expression and DNA repair." (PMID 38835346, 2024). "They observed a significant increase in ADC values in preoperative MRI scans of primary glioblastoma with MGMT promoter methylation." (PMID 38385046, 2024). "Recent efforts to predict MGMT methylation in a diverse glioblastoma MRI dataset highlight the need for larger, more standardized datasets to overcome data heterogeneity and improve model generalizability." (PMID 39375809, 2024). "Previous study reported that disulfiram, the parent precursor of DE, inhibited MGMT activity in human glioblastoma cell lines." (PMID 38720782, 2024). "Among these, Methyl-BEAMing technology has proven more effective in assessing MGMT promoter methylation in glioblastoma samples compared to MSP or pyrosequencing." (PMID 39594133, 2024). "Pharmacological inhibition of Connexin 43 or gap junction but also meclofenamate inhibition of intercellular cytosolic traffic via gap junctions reduced glioblastoma cell resistance to Temozolomide and Lomustine, independently of MGMT status." (PMID 38834748, 2024). "The combination of TMZ and CCNU for patients with methylated MGMT promoter yields good results and should be further investigated as a treatment option for recurrent glioblastoma." (PMID 39518091, 2024). "Studies have reported the high efficacy of both O6-BG-Glucose (O6-BG-Glu) and O6-BTG-Glu in inhibiting MGMT in various cancer cell lines, including T98G glioblastoma." (PMID 38254819, 2024). "In this study, multiple conventional MRI sequences (T1WI, T2WI, T2-FLAIR, CE-T1WI) were used to perform radiomics analysis based on imaging features provided by multiple tumor subregions for preoperative prediction of MGMT promoter methylation in glioblastoma." (PMID 38992201, 2024). "For these studies, we selected the T98G cell line because it is the best equivalent to glioblastoma according to its current definition carrying IDHwt phenotype, as well as being more aggressive and treatment-resistant regarding MGMT promoter methylation." (PMID 39273414, 2024). "MGMT methylation in diffuse gliomas serves as an important determinant of patients’ prognostic outcomes, more specifically in glioblastomas (GBMs)." (PMID 38203783, 2024). "MGMT methylation is also associated with IDH1 mutant tumours and therefore is more common in secondary than in primary glioblastoma (75% vs. 36% respectively)." (PMID 39767640, 2024). "MGMT methylation in glioblastoma is a good prognostic marker because these tumors have a significantly better response to temozolomide therapy compared to unmethylated tumors." (PMID 38798600, 2024). "These tests analyze tumor DNA and RNA to identify key genetic alterations, such as mutations in the IDH1 and IDH2 genes, MGMT promoter methylation, and EGFR amplification, which are pivotal in glioblastoma classification and prognosis." (PMID 39338377, 2024). "In the IDH-wildtype glioblastoma (GBM IDHwt) setting, hypermethylation of the MGMT promoter region has shown a consistent association with improved survival in response to TMZ." (PMID 38791984, 2024). "Several parameters are used to predict the theragnostic and orientation of treatment (efficacity of TMZ) of patients with glioblastoma, including epigenetic modification of the O6-methylguanine-DNA methyltransferase (MGMT) gene." (PMID 40093343, 2024).
glioblastoma (continued). "Aberrant methylation of the promoter region of the MGMT gene is of particular interest in glioblastoma patients, as it is frequently described as the most relevant predictor of response to alkylating agents such as temozolomide (TMZ)." (PMID 38357209, 2024). "Lastly, we investigated the linear relationship between glioblastoma-voxel location and the MGMT methylation percentage." (PMID 39713243, 2024). "The methylation status of oxygen 6-methylguanine-DNA methyltransferase (MGMT) is closely related to the treatment and prognosis of glioblastoma." (PMID 38385046, 2024). "In this study, we introduced a weakly supervised deep learning model based on H&E-stained histopathological slides to determine the MGMT promoter methylation status of glioblastoma." (PMID 38385046, 2024). "Decision curve analysis (DCA) and calibration curve show that the T1WIintra+peri + CE-T1WIintra+peri model was a reliable clinical treatment tool for predicting MGMT promoter methylation status in glioblastoma patients." (PMID 39716317, 2024). "The most notable effect was in a patient with primary IDH wild-type, MGMT promoter-unmethylated glioblastoma, with a PFS of 20.8 months and an OS of more than 24 months." (PMID 39239650, 2024). "Extent of resection, MGMT promoter methylation status, age, functional level, and residual tumor volume are established prognostic factors for overall survival in glioblastoma patients." (PMID 39531176, 2024). "Glioblastoma cells exhibiting elevated MGMT expression are capable of repairing the alkylation-induced DNA lesions, thereby diminishing their sensitivity to the cytotoxic effects of temozolomide." (PMID 39055560, 2024). "MGMT promoter hypermethylation is a validated biomarker for the efficacy of TMZ in glioblastoma, and is under active investigation in gastrointestinal malignancies, including colorectal cancers and biliary tract cancers." (PMID 39618336, 2024). "The CRISPR/Cas9 system, in conjunction with lipid-polymer hybrid nanoparticles (LPHNs-cRGD), was employed to achieve an efficient delivery of pCas9/MGMT plasmids into glioblastoma cells." (PMID 38254819, 2024). "The model demonstrates effective prediction of MGMT promoter methylation status in glioblastoma and exhibits some degree of generalization capability." (PMID 38385046, 2024). "MGMT promoter methylation testing is the most established molecular marker for response to temozolomide in IDH wild-type glioblastoma and in turn impacts overall survival." (PMID 39361075, 2024). "Collaborating with other healthcare organizations and research teams will help construct a more representative dataset, enhancing the model's ability to predict MGMT promoter methylation status for glioblastoma." (PMID 39716317, 2024). "In IDH-wt glioblastoma response to alkylating chemotherapy is significantly better when the MGMT promoter is methylated." (PMID 39560695, 2024). "The ‘Stupp trial’ and the RTOG0525 trial have provided definitive evidence for the prognostic significance of MGMT gene promoter methylation in patients newly diagnosed with glioblastoma multiforme (GBM)." (PMID 39055560, 2024). "In IDH-wildtype glioblastoma, the ROC AUC of detecting MGMT promoter hypermethylation of GLISP was 0.58 (95%CI = 0.49–0.66)." (PMID 39851286, 2024). "In glioblastoma, MGMT promoter methylation is common in females, with a subsequent better outcome after treatment with TMZ." (PMID 39767640, 2024). "Dexamethasone also reduces temozolomide-mediated apoptosis in human glioblastoma cells, possibly through O6-methylguanine-DNA methyltransferase (MGMT) upregulation, which results in an increased temozolomide resistance." (PMID 38611071, 2024). "In grade 4 glioblastoma multiforme (GBM), the wild-type IDH variant responds relatively well to TMZ, especially in patients with MGMT promoter methylation." (PMID 39439623, 2024).
glioblastoma (continued). "The study aims to explore MRI phenotypes that predict glioblastoma’s (GBM) methylation status of the promoter region of MGMT gene (pMGMT) by qualitatively assessing contrast-enhanced T1-weighted intensity images." (PMID 38410136, 2024). "When patients with glioblastoma received chemotherapy, patients with methylation of MGMT promoter results in longer survival compared to patients with unmethylated MGMT promoter." (PMID 38472373, 2024). "We included articles on adult glioblastoma that examined significant sites or regions within MGMT promoter for the outcomes: overall survival, progression free survival, and/or MGMT expression." (PMID 38521933, 2024). "The study investigated the methylation status of the entire MGMT promoter CGI using pyrosequencing and compared it with MGMT mRNA expression in a series of glioblastoma cell lines and xenografts." (PMID 38521933, 2024). "The MGMT promoter has been an important target in both newly diagnosed glioblastoma and recurrent glioblastoma as the protein product, AGT, yields resistance to alkylating chemotherapy such as TMZ." (PMID 38928445, 2024). "Temozolomide exerts a negligible therapeutic effect in patients with glioblastoma with an unmethylated MGMT promoter and has been omitted from first-line therapy in some clinical trials." (PMID 38390330, 2024). "The combination of IDH1-mut and MGMTp-met status is a more accurate predictor of survival in glioblastoma compared to either IDH1 or MGMT alone." (PMID 38893240, 2024). "Six months prior to the onset of his complaints, he was diagnosed with a grade IV glioblastoma accompanied by isocitrate dehydrogenases (IDH) mutation and O6-methylguanine-DNA methyltransferase (MGMT) promoter methylation." (PMID 38609860, 2024). "The 2018 NCCN guidelines clearly suggest that MGMT is an important prognostic and outcome predictor of glioblastoma." (PMID 38681199, 2024). "O-6-methylguanine-DNA methyltransferase promoter hypermethylation is a well-established biomarker for temozolomide response in glioblastoma patients, also correlated with therapeutic response in colorectal cancer." (PMID 39594133, 2024). "Consistently, numerous studies and trials have demonstrated a positive effect of MGMT promoter methylation in response to initial treatment with TMZ in newly diagnosed glioblastomas." (PMID 38928445, 2024). "The MGMT promoter methylation is a pivotal prognostic marker in glioblastoma, influencing patient responsiveness to alkylating chemotherapy agents like temozolomide (TMZ)." (PMID 39148521, 2024). "The literature here is scarcer, as most studies focus on MGMT in glioblastoma, due to its known impact on therapy response to temozolomide." (PMID 39335591, 2024). "Nonetheless, survival of 37 months in a case of MGMT-unmethylated glioblastoma is significantly above the expected median survival for this patient population." (PMID 39759633, 2024). "O6-methylguanine-DNA methyltransferase (MGMT) has been demonstrated to be an important prognostic and predictive marker in glioblastoma (GBM)." (PMID 38992201, 2024). "In this study, we report that DIAPH3 expression is positively correlated with overall survival of patients with MGMT-methylated glioblastoma." (PMID 38454929, 2024). "In glioblastoma, hypermethylation at the O6‐methylguanine DNA methyltransferase (MGMT) gene promoter is currently the most relevant biomarker predicting response to alkylating drugs." (PMID 39148319, 2024). "USP19 is overexpressed in glioblastoma patient samples, which positively correlates with the level of MGMT protein and poor prognosis in these patients." (PMID 38644551, 2024).
glioblastoma (continued). "Data from the phase 2 trials suggested promising antitumor activity as a single agent in recurrent glioblastomas and in combination with TMZ chemoradiotherapy in newly diagnosed, methylated MGMT promoter glioblastomas." (PMID 38892305, 2024). "The aim of our study is to understand the impact of MGMT methylation on inoperable IDH-wildtype glioblastoma patients who undergo biopsy and/or systematic treatment." (PMID 39367282, 2024). "This suggests that the use of multiple sequence model consisting of T1WI, CE-T1WI, and clinical factors to assess the MGMT promoter methylation status of glioblastoma can provide greater benefit to the patients involved." (PMID 39716317, 2024). "MGMT methylation is observed in patients with glioblastoma but more often in anaplastic oligodendrogliomas." (PMID 38674026, 2024). "The benefits of alkylating chemotherapy in elderly patients with newly diagnosed glioblastoma seem to be limited to patients with MGMT promotor methylation." (PMID 38571509, 2024). "A 2005 randomized trial showed that patients with methylated MGMT promoters had a greater survival benefit than patients with unmethylated MGMT promoters in glioblastoma patients treated with combination radiotherapy and temozolomide chemotherapy." (PMID 38681199, 2024). "We further devised a cox proportional hazard model that predicted the overall survival of these inoperable IDH-wildtype glioblastoma based on the statistically significant predictor variables namely MGMT status and treatment categories." (PMID 39367282, 2024). "Depletion of USP19 results in the glioblastoma cell sensitivity to temozolomide, which can be rescued by overexpressing MGMT." (PMID 38644551, 2024). "The ROI-based models of intratumoral and peritumoral regions, utilizing deep learning algorithms on multi-sequence MRI, were capable of predicting MGMT promoter methylation status in glioblastoma patients." (PMID 39716317, 2024). "The methylation status of the MGMT promoter serves as a critical predictive biomarker for glioblastoma responsiveness to temozolomide." (PMID 38891882, 2024). "This cross-sectional study aimed at investigating relationships between glioblastoma topology and MGMT promoter methylation, both as categorical (presence/absence) and continuous (percentage) status." (PMID 39713243, 2024). "Morning administration of temozolomide in glioblastoma increased OS in O6-Methylguanine-DNA-methyltransferase (MGMT) methylated patients, which was consistent with the peak expression of the clock gene BMAL1." (PMID 38585011, 2024). "CORE is a Phase 2 clinical trial in newly diagnosed glioblastoma in subjects with an unmethylated O6‐methylguanine‐deoxyribonucleic acid methyltransferase (MGMT) gene promoter in the tumor tissue." (PMID 38349028, 2024). "Methylation of the MGMT promoter increases the sensitivity to temozolomide in glioblastoma patients, extending their survival." (PMID 38454929, 2024). "MGMT (O 6 -methylguanine-DNA methyltransferase) promoter methylation is a commonly assessed prognostic marker in glioblastoma (GBM)." (PMID 38521933, 2024). "Clinical observations have substantiated that patients with glioblastoma characterized by a hypermethylated MGMT promoter exhibit a favorable response to temozolomide therapy." (PMID 39055560, 2024). "This study aims to evaluate the effectiveness of deep learning features derived from multi-sequence magnetic resonance imaging (MRI) in determining the O6-methylguanine-DNA methyltransferase (MGMT) promoter methylation status among glioblastoma patients." (PMID 39716317, 2024). "The study at hand indicates that a change in promoter methylation of MGMT, p15 and p16 between initial and relapse glioblastoma occurs in roughly one-third of the cohort." (PMID 39335591, 2024). "Another biomarker important in the prognostication of glioblastoma is O6-methylguanine-DNA methyltransferase (MGMT) methylation." (PMID 38396993, 2024).